PCYOX1L (prenylcysteine oxidase 1 like)
Description:
Prenylcysteine oxidase that cleaves the thioether bond of prenyl-L-cysteines, such as farnesylcysteine and geranylgeranylcysteine. Does not metabolize shorter prenyl chain compounds (Probable). Required in the mevalonate pathway to regulate prenylation and enhances the bactericidal activity of neutrophils (By similarity). Promotes the assembly of the postsynaptic ion channel ASIC1a (By similarity).
Synonyms: MGC3265
Tractability: Antibody: UniProt places it where antibodies can reach, with high confidence; its Gene Ontology location is reachable by antibodies, with high confidence; UniProt predicts a signal peptide or a membrane-spanning region. PROTAC: ubiquitination databases record sites on it; its protein half-life has been measured.
Gene: Protein-coding gene on chromosome 5 (149,358,002 to 149,369,653, forward strand). Ensembl gene ENSG00000145882.
Subcellular location: Secreted
Subcellular location (Human Protein Atlas): Mitochondria; Nucleoplasm; Predicted to be secreted
Pathways (Reactome):
Hemostasis: Platelet degranulation
Gene Ontology:
Molecular function: prenylcysteine oxidase activity; farnesylcysteine lyase activity; oxidoreductase activity, acting on a sulfur group of donors, oxygen as acceptor
Biological process: neutrophil-mediated killing of bacterium; prenylcysteine catabolic process
Cellular component: membrane; extracellular region; platelet alpha granule lumen
Genetic constraint (gnomAD): Loss-of-function variants: 40 observed, 44.36 expected, observed/expected ratio (o/e) 0.9, 90% interval 0.7 to 1.17. The upper end of that interval is the gene's LOEUF score, 1.17, which puts it in group 5 of 6, group 1 being the genes least tolerant of losing a copy. Missense variants: 592 observed, 643.05 expected, observed/expected ratio (o/e) 0.92, 90% interval 0.86 to 0.99. Synonymous variants: 262 observed, 276.87 expected, observed/expected ratio (o/e) 0.95, 90% interval 0.86 to 1.05.
Homologues: Orthologues: chimpanzee PCYOX1L (99% identical), macaque PCYOX1L (99% identical), guinea pig PCYOX1L (95% identical), rabbit PCYOX1L (95% identical), rat Pcyox1l (94% identical), mouse Pcyox1l (94% identical), dog PCYOX1L (90% identical), tropical clawed frog pcyox1l (67% identical), pig PCYOX1L (61% identical), zebrafish pcyox1l (50% identical). Paralogues in human: PCYOX1 (43% identical).
Diseases named in the same sentence as PCYOX1L in open-access papers:
PCYOX1L is named in the same sentence as 6 diseases in open-access papers, as found by Europe PMC text mining. Sharing a sentence is not in itself a finding about the gene and the disease. The quoted sentences say what the papers report.
Alzheimer disease (2 papers, 2012 to 2023). A progressive, neurodegenerative disease characterized by loss of function and death of nerve cells in several areas of the brain leading to loss of cognitive function such as memory and language. "The two genes LOC283755, also called HERC2P3, and PCYOX1L are not yet related to Alzheimer’s disease." (PMID 23066814, 2012).
infection (1 paper, 2023). The state of being infected such as from the introduction of a foreign agent such as serum, vaccine, antigenic substance or organism. "Cumulatively, our findings show that the Pcyox1l deficiency presents with altered prenylation and elevated susceptibility to infection." (PMID 37179332, 2023). "Among the identified network of infection and colonization-induced proteins was a previously uncharacterized protein termed Prenylcysteine oxidase-1-like protein (Pcyox1l)." (PMID 37179332, 2023). "Here the authors show a role for Pcyox1l and link this to metabolic pathways including prenylation and the neutrophil response to infection." (PMID 37179332, 2023). "In contrast, during infection the BM-derived Pcyox1l KO PMNs show inability to catabolize geranylgeranylcysteine when compared to WT BM PMNs harvested from P. aeruginosa infected mice, consistent with the expected enzymatic function for Pcyox1l." (PMID 37179332, 2023). "Pcyox1l knock-out mice demonstrate significant susceptibility to infection with the gram-negative pathogen Psuedomonas aeruginosa exemplified through increased neutrophil infiltrates, hemorrhaging, and reduced bactericidal functionality." (PMID 37179332, 2023). "In contrast to the homeostatic state, infection induced degradation of geranylgeranylcysteine substrates in the WT BM-derived PMNs, but not in the Pcyox1l KO PMNs." (PMID 37179332, 2023).
PCYOX1L also shares sentences with these, for which no sentence is quoted: clear cell renal cell carcinoma (1 paper); keratitis (1); neurodegenerative disease (1); parasitic infections (1).